SMARCB1 (SWI/SNF related BAF chromatin remodeling complex subunit B1)
Diseases named in the same sentence as SMARCB1 in open-access papers (continued):
Sharing a sentence is not in itself a finding about the gene and the disease.
tumor (continued). "Like most other SMARCB1-deficient neoplasms, the tumors display a monomorphic cytology lacking significant pleomorphisms or bizarre-looking nuclei." (PMID 35307773, 2022). "This epigenetic antagonism has been best characterized in SMARCB1-deficient MRT models where loss of SMARCB1 is associated with constitutive EZH2 activation and downstream oncogenic activity; in MRT preclinical models, EZH2 inhibition induced durable tumor regression and apoptosis." (PMID 35327458, 2022). "Interestingly, in Smarcb1 deficient cancer entities, ncBAF specific subunit BRD9 was identified as being essential for tumour cell proliferation, further supporting the idea that the ncBAF ensures cells’ survival by taking over cBAF functions." (PMID 35456033, 2022). "SMARCB1 modulates tumor cell immunogenicity through various mechanisms." (PMID 35327458, 2022). "Moreover, the reintroduction of SMARCB1 in MRT cells correlated with re-activation of tissue-specific lineage-determining genes, indicating that failure of differentiation underpins tumor development in a context of SMARCB1 deficiency." (PMID 36078034, 2022). "Most tumor cells showed diffuse expression for SMARCB1/INI-1." (PMID 36463108, 2022). "In contrast, brachyury staining was positive only in PDC samples, and was negative in other three SMARCB1/INI1-deficient tumor types." (PMID 35804041, 2022). "In total, we identified nine intrathoracic neoplasms with immunohistochemical loss of INI1 (SMARCB1), of which all were initially classified as intrathoracic neoplasms from either the lung (N = 3), lung/pleura (N = 1), pleura (N = 2), pleura/thoracic wall (N = 1) or mediastinum (N = 2)." (PMID 35864317, 2022). "In a Drosophila model, knockdown of Snr1 (the fly homologue of SMARCB1) in hedgehog activated cells not only altered hedgehog signaling, but also caused aberrant Notch signaling and formation of tumor-like structures." (PMID 35501487, 2022). "Given these seemingly conflicting pieces of data, it remains unclear how the WHD of SMARCB1 functions within the BAF complex and why germline mutations in the WHD predispose patients to tumor formation." (PMID 35892904, 2022). "Remarkably, there seems to be a striking organ-specific clustering of mutations in certain SWI/SNF genes, so that ARID1A mutations prevail in genital tract malignancies while SMARCB1 and SMARCA4 mutations predominate among SWI/SNF-driven neoplasms of soft tissue and lung, respectively." (PMID 35307773, 2022). "Further, mutations of the INI1 (SMARCB1) subunit of the switch/sucrose non-fermentable complex (SWI/SNF) have been thought to lead to EZH2-dependent tumor formation." (PMID 34067530, 2021). "In t-SNE analyses, ATRT-SMARCA4 grouped overall together with SMARCB1-deficient RTs and SCCOHTs, but did not locate specifically within one of these tumor subclasses." (PMID 33331994, 2021). "Among the remaining 4 SWI/SNF‐deficient UEC, 1 of 3 SMARCA4‐deficient tumors, and 1 SMARCB1‐deficient tumor were MMR‐deficient and none of the reported cases of SMARCA4‐deficient rhabdoid uterine sarcoma occur in a MMR protein‐deficient context." (PMID 33125840, 2021). "Disruption of the NES, however, not only restored nuclear location of truncated SMARCB1 protein, but also induced senescence in the senescent cell assay and SA-β-gal assay, suggesting residual tumor suppressor function of the truncated protein, if nuclear location can be achieved." (PMID 34003336, 2021).
tumor (continued). "SMARCB1-deficient non-MRT neoplasms of childhood represent an expanding spectrum of diseases including highly aggressive but also low-grade neoplasias such as undifferentiated chordomas, epithelioid sarcomas, epithelioid MPNST, and other rare entities." (PMID 33532948, 2021). "Notably, tumor cells showed a heterogeneous loss of SMARCA4 expression pattern and intact SMARCB1 expression." (PMID 33836796, 2021). "The histological examination of the lesion biopsy documented a GFAP+ highly cellular neoplasm, with no mutation on SMARCB1 gene." (PMID 34906194, 2021). "In three of the cases showing distinct cytoplasmic SMARCB1 staining of tumor cells, germline SNVs/indels C-terminal of the NES could be demonstrated." (PMID 34003336, 2021). "Individuals with CSS carrying SMARCB1 or SMARCA4 mutations seem to show no predisposition to develop RTs or other forms of tumor." (PMID 33692948, 2021). "Therefore, they should be classified as SMARCB1 deficient medullary RCC, a highly aggressive tumor in young patients with a sickle cell trait (with hypoxia of papillae caused by this condition possibly linked to tumorigenesis)." (PMID 34680535, 2021). "Negative associations were enriched in pathways of the SMARCB1 tumor suppressor, DNA methylation, and the proteasome." (PMID 33889302, 2021). "Based on these observations, we hypothesized that cytoplasmic localization of truncated SMARCB1 protein in ATRT could be due to nuclear export sequence unmasking, which in turn may cause loss of tumor suppressor function." (PMID 34003336, 2021). "Interestingly, each of the four mutants M1–M4 exhibited defective capacity to inhibit tumor growth as compared to WT SMARCB1, indicating that these mutants have lost, at least in part, their tumor-suppressive activity." (PMID 33024572, 2020). "Currently, SMARCB1 is classified into Tier 1 of the Cancer Gene Census as a tumor suppressor gene." (PMID 32380731, 2020). "Despite theSMARCB1/INI1 gene being discovered in the mid-1990s, the majority of previous reports were excluded for not mentioning the tumor’s SMARCB1/INI1-deficiency status." (PMID 33796273, 2020). "The term ‘MERT’ is applied to primitive malignant tumours indicating rhabdoid histomorphology even if it is partial, loss of SMARCB1 protein and/or SMARC1 gene mutation, and without any other line of differentiation." (PMID 33520482, 2020). "In some cases, a mix of grape-like clumps of cells and more cystic organoid structures was observed, pointing towards contamination of the tumour organoid culture with organoids derived from normal kidney epithelium, which was confirmed by staining for SMARCB1." (PMID 32161258, 2020). "Moreover, ezrin is a downstream target of SMARCB1/INI1, regulator of chromatin remodeling, and potential tumor suppressor." (PMID 32317857, 2020). "In light of SMARCB1 being a bona fide tumor suppressor, it is not surprising that loss of INI1 expression has been identified as a negative prognostic factor in other malignancies." (PMID 32380731, 2020). "SDSC is a rare, often fatal tumor characterized by distinct inactivating alternations of the tumor suppressor gene SMARCB1 located on chromosome 22q11.2, basaloid/rhabdoid differentiation, and histologic loss of INI1 expression." (PMID 31438887, 2019). "Moreover, and consistent with its established role as a CNS tumor suppressor, we find that SMARCB1 is essential for neural induction but dispensable for mesodermal or endodermal differentiation." (PMID 31033435, 2019). "SMARCB1/SNF5 is a tumour suppressor and component of the SWI/SNF chromatin remodeler." (PMID 31043611, 2019). "SMARCB1 normally acts as a so-called tumor suppressor, preventing cells from becoming cancerous." (PMID 30860482, 2019).
tumor (continued). "Similarly, we observed an enrichment of SMARCE1 and SMARCB1, two proteins that are core components of the BAF (SWI/SNF) chromatin remodeling complex and have been implicated as inhibitors of tumor formation." (PMID 30046396, 2018). "Rhabdoid tumors and cell lines lack INI1 (SMARCB1/SNF5) tumor suppressor." (PMID 30201866, 2018). "A variety of neoplasms have been discovered to have genomic alterations (GAs) and loss of immunohistochemical (IHC) expression of chromatin remodelers ARID1A (BAF250A), SMARCA2 (BRM), SMARCA4 (BRG1), and SMARCB1 (INI1)." (PMID 31093468, 2018). "SMARCB1 (INI1) is a tumor-suppressor gene located at 22q11.2." (PMID 29625594, 2018). "A variety of neoplasms have been discovered to have genomic alterations and loss of immunohistochemical (IHC) expression of chromatin remodelers ARID1A (BAF250A), SMARCA2 (BRM), SMARCA4 (BRG1), and SMARCB1 (INI1)." (PMID 31093468, 2018). "In addition, some tumours can now be identified by molecular genetic analysis, for example NUT (NUclear protein in Testis) carcinoma and SMARCB1 (INI-1) deficient sinonasal carcinoma." (PMID 29507386, 2018). "LOH of 22q in tumours from patients with germline SMARCB1 mutations does not seem to be mediated by mitotic recombination, a mechanism frequently causing LOH of other tumour suppressor genes." (PMID 27921248, 2017). "With mutations in genes encoding SWI/SNF subunits (for example, ARID1A, ARID1B, ARID2, PBRM1, SMARCA4 and SMARCB1) collectively occurring in ∼20% of all tumours whose genomes have been characterized to date, SWI/SNF complexes are the most commonly mutated chromatin modulators in human cancer." (PMID 28262751, 2017). "Hence, SMARCB1 plays the role of a classic tumour suppressor gene in rhabdoid tumours according to the Knudson two-hit model." (PMID 27921248, 2017). "In this subgroup of tumours, the inactivation of only one NF2 allele may be sufficient to promote the proliferation of the cells with biallelic SMARCB1 inactivation." (PMID 27921248, 2017). "This tumor is characterized by noncohesive tumor cells with eccentric nuclei and eosinophilic cytoplasm morphologically and deletion/mutation of the SMARCB1/INI1 gene located on chromosome 22q 11.2 genetically." (PMID 29258531, 2017). "However, comprehensive mutation testing of LZTR1, SMARCB1, and NF2 using DNA derived from blood and different tumour samples of the patient is the method of choice to distinguish between the two conditions." (PMID 27921248, 2017). "Notably, however, deletion of either of the Smarcb1 or Smarca4 tumour suppressor subunits in MEFs markedly reduced interactions between p300 and the core SWI/SNF subunit Smarcc1." (PMID 28262751, 2017). "Therefore, a diagnosis of Xp11.2 translocation RCC with SMARCB1 inactivation is proposed in this double hit tumor concerning the histopathological features and TFE3 rearrangement." (PMID 27733182, 2016). "The gene hSNF/INI1/SMARCB1/BAF47 is a putative tumor suppressor gene expressed in all normal cells." (PMID 27733182, 2016). "The unexpected heterogeneity within hIC tumours may then reflect that various stem or progenitor cells are able to survive to Smarcb1 inactivation, and subsequently give rise to significantly different tumours." (PMID 26818002, 2016). "Accumulating data suggest that tumors with rhabdoid features contain a clinicopathological spectrum of neoplasms with a highly variable rhabdoid cell component, with or without the loss of nuclear SMARCB1 expression." (PMID 27733182, 2016). "We therefore postulated that Smarcb1 inactivation at E6-E10 may target such stem or progenitor cells, as cells of origin of the tumours." (PMID 26818002, 2016).
tumor (continued). "Moreover, we show that early embryonic inactivation of Smarcb1 leads to a fully penetrant model of tumours, mainly intra-cranial, which faithfully resemble human RTs and recapitulate some of their diversity." (PMID 26818002, 2016). "So, despite often only carrying a seemingly simple genetic alteration, leading to the inactivation of SMARCB1, AT/RT tumours are heterogeneous when it comes to the transcripts/pathways affected and this may be reflected in patient outcome." (PMID 26998479, 2015). "Interestingly, many of the SL interactions that are extrapolated from lower-order organisms turn out to be tumour-suppressor genes (e.g. SMARCB1, see Introduction) and these are rarely altered in human cancers." (PMID 26427375, 2015). "Among these, the most likely tumour causing event in this patient seems to be a germline nonsense mutation in SMARCB1 gene, c.601C>T p.Arg201∗." (PMID 26998479, 2015). "We describe Smarcb1 dependent constitutive phosphorylation of the EGFR, which is also transcriptional elevated in Smarcb1 deficient cells and demonstrate that inhibition of the EGFR/ERBB signaling pathway inhibits proliferation of Smarcb1 deficient tumor cells." (PMID 26370283, 2015). "After that, the whole coding sequence of NF2 and SMARCB1 genes were sequenced in tumor T1." (PMID 25739810, 2015). "The SWN tumor tissue and corresponding cell line exhibit similar SMARCB1 expression levels." (PMID 26657314, 2015). "As proof that the retained genes include genuine drivers, we note that the list of genes recurrently lost in both human and fish MPNSTs includes four tumor suppressors, NF1, NF2, SMARCB1 and PTEN, that are strongly associated with the development of human Schwann cell tumors." (PMID 24009526, 2013). "However, SMARCB1 is also known to be important in antiviral activity, inhibition of tumour formation, neurodevelopment, cell proliferation and differentiation." (PMID 23382691, 2013). "Thus, the cytoplasmic localization of SMARCB1 eliminates its tumour suppressor function." (PMID 40794298, 2025). "In adult tumours, SMARCB1 may have a more multifaceted, even oncogenic role." (PMID 40794298, 2025). "In the tumor tissue, there is a fibrous tissue wrapping, and tumor cells invade and break through part of the envelope There is also the presence of cancer thrombi in the surrounding blood vessels.SMARCB1/INI-1 immunohistochemistry assays are used to assess the expression of INI-1 protein." (PMID 40115023, 2025). "In our case of SMARCB1-deficient PXA, the nodule of the cystic wall showed slightly and not uniformly enhanced, which maybe a distinguished feature of SMARCB1-deficient PXA from the other PXA or indicate the malignancy of the tumor on imaging." (PMID 40231261, 2025). "The STAT3 inhibitor TTI-101 was shown to effectively inhibit tumor growth in SMARCB1-deficient BLCA patient-derived xenograft mice without significant weight loss, providing a strong preclinical rationale for using TTI-101 as a therapeutic strategy for SMARCB1-deficient BLCA." (PMID 40115023, 2025). "A recent study in bladder cancer showed that SMARCB1-deficient tumours displayed increased IL6–janus kinase–signal transducer and activator of transcription 3 (IL6-JAK-STAT3) signalling in in vivo models and patient tumours, believed to be associated with metastasis." (PMID 40422882, 2025). "The deletion of the SMARCB1/INI1 was confirmed by immunohistochemistry the following features can be observed: i) Tumor cell morphology shows diffuse distribution of atypic cells in tumor tissues, enlarged nuclei, increased nucleocytoplasmic ratio and an irregular nuclear membrane." (PMID 40115023, 2025). "This combination was motivated by previous reports that ATRT has aberrant H3K27ac downstream of SMARCB1 inactivation, that is met with elevated DNA methylation over these sites, and that hypomethylation and hyperacetylation can elicit innate immune signaling in other tumor types." (PMID 41408661, 2025).
tumor (continued). "Moreover, we assessed the correlation of clinicopathological features (age, gender, tumor size, tumor location, surgical margins, Ki67 labelling index, SMARCB1/INI1 pattern, previous surgery, previous treatment, type of surgery, and the Charlson Comorbidity Index) with patient survival." (PMID 39199581, 2024). "A new tumor type has been recognized in addition to the four known tumor types [pineal parenchymal tumor of intermediate differentiation (PPTID), pineoblastoma, and papillary tumor of the pineal region]: the “desmoplasic myxoid tumor of the pineal region with SMARCB1 mutation”." (PMID 39135755, 2024). "This hypothesis, however, conflicts with the established tumor suppressor role of SMARCB1." (PMID 35892904, 2022). "On univariate analyses, longer overall survival was also associated with older age (> 3 years) and positive ASCL1 staining, but not OLIG2 or GFAP staining, tumor location, gross total resection or the presence of pathogenic/likely pathogenic SMARCB1 germline variants." (PMID 35501487, 2022). "Despite the presence of two independent tumor lineages and as many as five distinct clones, no new diagnostic, prognostic, or therapeutically applicable SNVs or CNVs were found in any clones beyond the SMARCB1 events." (PMID 35912263, 2022). "These neoplasms are thought to be driven by a loss of SWItch/sucrose non-fermentable (SWI/SNF)-related matrix-associated actin-dependent regulator of chromatin subfamily B member 1 (SMARCB1), also known as integrase interactor 1 (INI1)." (PMID 36262954, 2022). "This would suggest that SMARCB1 loss on its own may not suffice to generate tumours, or to prevent normal cellular differentiation." (PMID 33658498, 2021). "Notably, tumor cells showed loss of SMARCA4 protein and intact SMARCB1 protein expression." (PMID 33836796, 2021). "Nonetheless, the panel argues that patients with “SMARCB1-deficient non-RT neoplasms” should be offered genetic testing on a research basis and, if positive for a PV, cancer surveillance ideally in the setting of a tumor predisposition clinic." (PMID 33532948, 2021). "In addition, some tumours can now be identified by molecular genetic analysis, for example, NUT (NUclear protein in testis) carcinoma and SWI/SNF chromatin remodelling complex, particularly its subunits SMARCA4 (BRG1)- and SMARCB1 (INI-1)-deficient carcinomas." (PMID 34573868, 2021). "We hypothesize that loss of SMARCB1 chromatin remodeling coupled with enhanced C-MYC binding to the HML-2 LTR results in constitutive expression of HML-2 elements, allowing cells to maintain a stem-cell like identity and persist as this developmental tumor." (PMID 34145313, 2021). "Finally, due to low tumor purity, we did not identify mutations or deletions/translocations in the SMARCB1 gene despite the loss of SMARCB1 by immunohistochemistry in PAWMTU and PAXBXE." (PMID 34261517, 2021). "SMARCB1 therefore appears to function largely as a transcriptional repressor in hESCs, particularly at bivalent genes, in contrast to what has been reported in experiments in mouse embryonic fibroblasts (MEFs) and several null tumor cell lines, including TTC-1240." (PMID 31033435, 2019). "The classical two-hit model of tumorigenesis does not seem to pertain in the tumours of patients with SMARCB1 germline mutations, at least in the sense that this model would require biallelic SMARCB1 inactivation to be sufficient for tumour initiation or growth." (PMID 27921248, 2017). "In these tumours, neither SMARCB1 nor LZTR1 mutations were detected." (PMID 27921248, 2017). "This may be concluded from the observation that the loss of the wild-type SMARCB1 allele is readily detectable by loss of heterozygosity (LOH) analysis using polymorphic markers, suggesting that this loss affects a large proportion of tumour cells." (PMID 27921248, 2017).